IL10 (interleukin 10)
Diseases named in the same sentence as IL10 in open-access papers (continued):
Sharing a sentence is not in itself a finding about the gene and the disease.
pulmonary TB (continued). "In the event of TB progression, over-expression of IL-10 results in a higher mycobacterial burden and reactivation of pulmonary TB." (PMID 21447195, 2011). "IL-10 differentiated pulmonary tuberculosis patients from latent cases with an AUC of 0.731." (PMID 32962082, 2020). "As such, the present study determined circulating IFN-γ, IL-10, and adiponectin levels and their association with clinical manifestations of early stage disease in non-substance using newly diagnosed pulmonary TB cases." (PMID 26880909, 2016). "The aim of our study was to investigate whether IL6–174 G>C SNP and IL17A -197 G>A polymorphism and additional cytokine genes involved in immune response to MTB (IL2, IL4, IL10, IFNG and TNF) are associated with genetic susceptibility to pulmonary TB (PTB)." (PMID 26840977, 2016). "Thus, active pulmonary TB appears to be characterized by an antigen-responsive expansion of IL-10+ CD4+ T cells that also are producing more IL-10 per cell." (PMID 26417443, 2015). "In contrast to our results, studies have shown that patients with a recent diagnosis of pulmonary tuberculosis present higher serum levels of IL-10 than do previously treated or healthy individuals, although treatment reduces the serum concentration of this cytokine." (PMID 24558401, 2014). "Within this scenario, the strong positive correlation of IFN-γ and TNF-α with IL-10 production during the establishment of clinical cure of pulmonary tuberculosis seems to contribute to the control of the microorganism without inducing exacerbated tissue damage." (PMID 23824716, 2013). "Thus, Th2 responses are equally compromised in active pulmonary TB and these responses are modulated similar to Th1 responses by immunoregulatory mechanisms, especially IL-10." (PMID 23544075, 2013). "High levels of IL-10 may prevent collateral tissue damage particularly in the lung during the chronic phase of pulmonary TB but may lead to disease activation during the early or latent phase of infection by down regulating both TNF-α and IFN-γ." (PMID 22140472, 2011). "Therefore, the aim of this study was to verify if IFNG, IL12B, TNF, IL17A, IL10, and TGFB1 gene polymorphisms influence the immune response of Brazilian patients with pulmonary tuberculosis (PTB) at different time points of antituberculosis treatment (T1, T2, and T3)." (PMID 23634300, 2013). "Hence, whether or not the production level of IFN-γ and IL-10 might influence susceptibility or severity in pulmonary TB among Kelantanese Malay ethnic is unknown." (PMID 40487054, 2025). "In the comparison of median cytokine levels between patients with pulmonary TB and extrapulmonary TB, the extrapulmonary TB group had significantly lower levels of IFN-γ (p < 0.0001), IL-2 (p = 0.0368), IL-10 (p = 0.0373) and IL-17 (p = 0.0326)." (PMID 36296351, 2022). "In active pulmonary TB patients with high bacterial burden, miR-23a-3p expression was decreased, affecting the balance between TLR4 and IL10 immunologic responses by down-regulating SP1/IRF1 expression and further influencing TLR4/IL10 expression ratio." (PMID 33202583, 2020). "Therefore, TYK2 may involve in the pathogenesis of pulmonary TB via regulating IL-10." (PMID 27655333, 2016). "Elevated levels of IL-10 and TGF-β were found in bronchoalveolar lavage fluid and comprised mainly macrophages and neutrophils, in pulmonary TB patients." (PMID 24350246, 2013). "Patients with pulmonary TB show elevated levels of IL-10 in lungs, serum, sputum, and bronchoalveolar lavage (BAL) fluid, suggesting a role for IL-10 in preventing control of Mtb infection." (PMID 23869227, 2013). "Increased levels of IL-10 and Mtb antigen CFP32 were observed in the sputum of pulmonary TB patients suggesting a positive correlation between IL-10 and the progression of disease." (PMID 24350246, 2013).
pulmonary TB (continued). "The objective of the current study was to analyze IFN-γ gene combinations with other IFN-γ regulating cytokine genes (IL-10, TNF –α, IL-6) to see the effect of gene- combinations on disease severity outcome in pulmonary tuberculosis." (PMID 22140472, 2011). "It has been found that high serum IL-10 levels in patients with pulmonary TB lead to a slower response to treatment and a lack of bacterial control, thereby underlining the importance of a strong pro-inflammatory response when lung tissues are still intact." (PMID 29740435, 2018). "We determined interferon-gamma, interleukin-10, and adiponectin levels in clinically and phenotypically well-characterised non-substance using new pulmonary tuberculosis patients (n = 13) and controls (n = 14) from Kenya." (PMID 26880909, 2016). "In summary, we extend our previous findings on the cytokine profile of αE-DC during pulmonary TB and show that αE-DC are potent IL-12p40-producing, but not IL-10-producing cells in the M. tuberculosis-infected lungs." (PMID 23861965, 2013). "It has been found that the combined production of the immunosuppressants IL-10 and TGF-β in patients with pulmonary tuberculosis may reduce host immunity against Mycobacterium tuberculosis, resulting in uncontrolled bacterial replication and causing overt disease." (PMID 38572322, 2024). "To further characterize the effect of vaccination on pulmonary TB pathogenesis, we evaluated the production of TNF-α, IL-17, and IL-10 in lungs of vaccinated/non-vaccinated and infected guinea pigs." (PMID 34127755, 2021). "For identification of adult pulmonary TB, regardless of HIV status, we identified an 8-marker signature consisting of FGF, IL-1β, IL-8, IL-10, IL-12p70, IL-13, MIP-1β and VEGF which gave an AUC of 0.78 (95% CI: 0.75, 0.84), sensitivity of 79% (95% CI: 75, 84) and specificity of 67% (95% CI: 60, 73)." (PMID 41164199, 2025).
Thrombocytopenia (55 papers, 2012 to 2026). A reduction in the number of circulating thrombocytes. "It is also important to note that compared to DLBCL, PEL has a higher degree of association with hypoalbuminemia, thrombocytopenia, and elevated IL-10 levels." (PMID 35158997, 2022). "Our data also demonstrate that thrombocytopenia is associated with an increase in IL-1, IL-6, IL-8, IL-10, and TNF-α." (PMID 34585667, 2021). "In another study, thrombocytopaenia in patients with P. vivax infection was associated with increased IL-1, IL-6, IL-10, and TGF-β." (PMID 30126413, 2018). "In a recent study, thrombocytopenia was associated to elevated levels of IL-27, IL-10 and IL-6 cytokines." (PMID 28231825, 2017). "A subset of cytokines consisting of IL-1β, IL-8, IL-6, TNF-α, and IL-10 was also coordinately high and significantly associated with severity of thrombocytopenia in HA patients." (PMID 28628633, 2017). "It is possible that similar mechanism of reduced platelet production due to high IL-10 levels is responsible for P. vivax-associated thrombocytopaenia in this study." (PMID 25128199, 2014). "In addition to IL-10, our analysis identified IL-1Ra as associated with P. vivax-severe thrombocytopenia." (PMID 33791239, 2021). "Another observed effect of these cytokines (IL-10) is the increase in ferritin and the reduction in the number of platelets (thrombocytopenia)." (PMID 40005520, 2025). "Regarding anti-inflammatory cytokines, IL-10 was found to be elevated in patients with thrombocytopenia compared to those with normal platelet counts." (PMID 40690473, 2025). "Further studies are needed to understand the mechanism of regulation mediated by this cytokine, its protective effect against thrombocytopenia and its interaction with IL-10." (PMID 40690473, 2025). "Patients with IBD receiving purified IL-10 have adverse effects such as hemoglobin reduction or thrombocytopenia, limiting its therapeutic utility." (PMID 36110841, 2022). "Supervised machine learning spotlighted IL-10 in P. vivax-mediated thrombocytopenia and provided evidence for a potential signaling route involving IL-8 and HGF." (PMID 33791239, 2021). "Collectively, these results indicate that hepatocyte-derived IL-10 plays an important role in attenuating erythrophagocytosis, hemodilution as well as thrombocytopenia." (PMID 32012211, 2020). "In comparison with NT groups, the IL-10 levels were found to be significantly increased across varying intensity of thrombocytopenia during Pv, Pf, and mixed infections." (PMID 31110658, 2019). "In this study, similar to earlier reports, patients with severe thrombocytopenia were also found to have increased IL-10 levels across various infecting species, implying a similar role of IL-10 in decreased platelet levels." (PMID 31110658, 2019). "IL-6, IL-10 and TNF production has been associated with thrombocytopenia in P. vivax malaria patients." (PMID 30199554, 2018). "Several host factors including cell-mediated immune cells, such as IL-1, IL-6 and IL-10 have been documented for P. vivax-induced thrombocytopaenia." (PMID 25128199, 2014). "Recently, a study showed that the administration of IL-10 to healthy volunteers was capable of inducing thrombocytopenia." (PMID 23723981, 2013). "SFTSV infection itself was speculated to induce immunosuppression and lead to secondary infection as a result of leukopenia, thrombocytopenia, and interleukin 10 overexpression." (PMID 33925061, 2021). "This increased hemodilution resulted in thrombocytopenia, encompassing a decrease in platelet counts per blood volume and in the absolute platelet number in the blood of the respective mice, which is again most pronounced in TgAlbCre-IL10-/- mice." (PMID 32012211, 2020). "However, the level of IL-10 has been found to be significantly correlated with thrombocytopenia in Ebola virus infection." (PMID 25066751, 2014). "Moreover, a fatal CCHF case that had a high level of IL-10 and severe thrombocytopenia has been defined." (PMID 25066751, 2014).
Thrombocytopenia (continued). "Actually, it has been shown that thrombocytopenia in children with acute falciparum malaria is strongly associated with plasma concentrations of IL-10, but not with P. falciparum parasitemia or other plasma cytokines." (PMID 23723981, 2013). "Moreover, other predictors of fatality included higher interleukin-10, lower albumin, and higher lactate dehydrogenase levels in serum, as well as central nervous system involvement and/or presence of thrombocytopenia, but also persistent hyperferritinaemia during the time of treatment." (PMID 40572665, 2025). "Therefore, intrinsic IL-10 response induced in response to protecting the host against injury results in down regulation of platelet production mechanisms, thus leading to manifestation of thrombocytopaenia." (PMID 25128199, 2014). "SFTSV infection triggers a cytokine storm (e.g., elevated IL-6, IL-10, TNF-α), resulting in direct vascular endothelial damage and increased permeability, which contribute to thrombocytopenia and multiorgan dysfunction." (PMID 40794812, 2025). "A high IL-10 to TNF-α ratio, observed in the control group of both studies, and severe thrombocytopenia observed in the control group of Study 1, indicative of acute leptospiral disease, were detected." (PMID 40732660, 2025). "We also observed a distinct cytokine profile in patients with thrombocytopenia (MT group), characterized by elevated IL-6, IFN-γ, and IL-10 levels, along with reduced TGF-β1." (PMID 40690473, 2025). "Our findings reveal significantly elevated sCP levels in SFTS patients, positively correlated with viral load, thrombocytopenia severity, and multiple pro-inflammatory cytokines (TNF-α, IL-6, IL-8, IL-10)." (PMID 40657502, 2025). "Severe thrombocytopenia was positively correlated with IL-4, CXCL10, IL-6, IL-10 and IFN-γ levels, renal dysfunction was related to an increase in IL-2, IL-1β, IL-17A and IL-8, and hepatic impairment with CXCL10, MCP-1, IL-6 and IFN-γ." (PMID 36178979, 2022). "The CRS was evidenced by raised inflammatory markers, thrombocytopenia, elevated cytokine levels (IFN-γ/IL-2R/IL-18/IL-16/IL-10) and steroid responsiveness." (PMID 34040262, 2021). "In this study, the samples were analyzed for the prevalence and assessment of degree of thrombocytopenia, as well as for cytokines such as TNF-α, IL-6, and IL-10." (PMID 31110658, 2019). "Association of cell-mediated immune cells, such as interlukin-1 (IL-1), IL-6, IL-10, tumour necrosis factor (TNF) and transforming growth factor-β (TGF-β) and thrombocytopaenia have been documented in various studies." (PMID 25128199, 2014). "This was further supported by a dysregulated cytokine profile, characterized by elevated levels of IFN-γ, IL-6, and IL-10 in patients with thrombocytopenia compared to those without." (PMID 40690473, 2025). "In the MT group, the regulation should be mediated by IL-10, although it seems that this effect is not efficient in preventing thrombocytopenia." (PMID 40690473, 2025). "Additionally, EIII-SNPs induce exacerbated thrombocytopenia, worsen hemorrhage pathogenesis, and the induction of pro-inflammatory cytokines TNF-α, IL-1β, IL-6, and anti-inflammatory cytokine IL-10 in mice." (PMID 37298220, 2023). "In contrast, PedSep-D had the most profound inflammatory response with highest M-CSF, IL-8, SCF, sCD163, IL-16, IL-10, TNF, and MIP1α levels, and thrombotic microangiopathic response with lowest ADAMTS13 activity decreased to < 57% of control with thrombocytopenia." (PMID 35526000, 2022). "Au and colleagues presented a patient with fever, thrombocytopenia, CRP increase and elevation of several cytokines including interferon-γ, sIL-2R, IL-18, IL-16 and IL-10 after vaccination and ICI therapy compared to cytokine levels before initiation of ICI therapy and vaccination." (PMID 35715501, 2022).
Thrombocytopenia (continued). "Irrespective of infecting species, the IL-6/IL-10 ratio also showed a significant decrease with an increase in thrombocytopenic intensity, especially during severe thrombocytopenia." (PMID 31110658, 2019). "The finding that thrombocytopenia lowered both T-cell infiltration and IL-10 levels after TAC suggested that platelets may be influencing T-cell-mediated events in an IL-10-dependent manner in this model." (PMID 22916095, 2012). "Although previous studies highlight that IL-10 has complex and not well-characterized functions in P. vivax pathogenesis, our findings strengthen this cytokine’s critical contribution in P. vivax-induced thrombocytopenia." (PMID 33791239, 2021). "The main sources of IL-10 release are virus immune complex infected macrophages, memory cells, and infected monocytes, which may explain the observation that IL-10 does not decrease with thrombocytopenia." (PMID 28929009, 2017). "Additionally, a high IL-10 to TNF-α ratio, combined with thrombocytopenia, constitutes a non-specific marker of acute leptospirosis in symptomatic and asymptomatic infections." (PMID 40732660, 2025). "In mild-grade CLP, clopidogrel- and vehicle-treated mice did not display a significant decrease in MAP, while thrombocytopenia and plasma concentrations of TNFα, IL6, IL10, MPO, TAT and organ damage reached similar levels in both groups, although lower than those reached in the high grade CLP." (PMID 34447900, 2021).
enteritis (54 papers, 2009 to 2026). Inflammation of the small intestine. "Studies have shown that IL-10-deficient mice have increased C. jejuni colonization and enteritis and IL-10 suppresses the clinical infection and production of proinflammatory cytokines." (PMID 35862957, 2022). "Our results are in accordance with these findings in that strains D0835 and D2600, which were able to cause enteritis in C57BL/6 IL-10-/- mice, were iam-." (PMID 19296832, 2009). "The results reported here show that C. jejuni strains from humans, chickens, and cattle vary in their ability to colonize and cause enteritis in C57BL/6 IL-10-/- mice." (PMID 19296832, 2009). "Our previous findings indicated that excessive generation of CD4+IL-10+ T cells induced by oral administration of BLS-mix to newly weaned MUC4 RR pigs with enteritis caused by an enteric pathogen might prohibit clearance of the pathogen." (PMID 27424033, 2016). "Our second hypothesis was that serial passage of C. jejuni strains in C57BL/6 IL-10-/- mice would increase the ability of the passaged strains to cause enteritis in mice." (PMID 19296832, 2009). "Our first hypothesis was that C. jejuni strains from humans, chickens, and cattle vary in their ability to colonize and cause enteritis in C57BL/6 IL-10-/- mice." (PMID 19296832, 2009). "Initial ability of C. jejuni strains to colonize and cause enteritis in C57BL/6 IL-10-/- mice." (PMID 19296832, 2009). "Enteritis in a neonate might be due to IL-10 and IL-10 receptor deficiencies." (PMID 32082296, 2019). "By contrast, A20ZF7 mice develop enteritis in the presence of supranormal levels of Tregs and IL-10." (PMID 40892518, 2025). "Colonization of AKK in GF IL10−/− mice decreases mucous layer thickness and induces inflammatory cytokines, exacerbating enteritis." (PMID 40305678, 2025). "In this experiment, the levels of TNF-α, IL-1β, IL-6, and IL-10 in the mouse colon were measured using ELISA kits to assess the impact of different treatments on inflammatory factors in murine enteritis." (PMID 39697653, 2024). "Studies have shown that IL-10 knockout mice have spontaneous enteritis, suggesting that the occurrence of UC is related to the reduction of IL-10." (PMID 37457023, 2023). "IL-10 gene-deficient mice (IL10 -/- mice) and macrophage-specific Stat3-deficient mice (LysM-cre; Stat3 f/- mice) spontaneously develop enteritis." (PMID 36845090, 2023). "While LPS can reduce colon level of IL-10, HMW oat β-d-glucans fed to LPS-induced enteritis mice were able to normalize IL-10 and thus reduce pro-inflammatory cytokines IL-2 and TNF-α." (PMID 36981048, 2023). "Fraxetin was reported to mitigate the levels of IL-1β, IL-6, TNF-α and prostaglandin E2, improve the content of superoxide dismutase (SOD) and IL-10 in rats with enteritis." (PMID 37161415, 2023). "Previous studies have shown that probiotics can significantly reduce the levels of IL-1β and IL-6 and increase the level of the anti-inflammatory cytokine IL-10 in the serum of mice with enteritis, thereby alleviating intestinal inflammation." (PMID 37817260, 2023). "Interleukin-10 (IL-10) is an inflammatory and immunosuppressive factor that plays a vital role in controlling inflammation and preventing enteritis." (PMID 35241180, 2022). "In our previous study, we found a normalization of IL-10 concentration in rats with enteritis after supplementation with oat beta-glucans." (PMID 33923129, 2021). "The effective treatment of acute C. jejuni induced enteritis in microbiota-depleted IL-10−/− mice by rapamycin indicates that the suppression of the excessive innate immune responses constitutes a promising approach for novel intervention strategies." (PMID 33807493, 2021). "We used BPTES to inhibit Gls1 expression and explored the role of Gls1 in enteritis in IL‐10−/− mice in the following study." (PMID 31211512, 2019).